PRMT6 (protein arginine methyltransferase 6)
Description:
Arginine methyltransferase that can catalyze the formation of both omega-N monomethylarginine (MMA) and asymmetrical dimethylarginine (aDMA), with a strong preference for the formation of aDMA. Preferentially methylates arginyl residues present in a glycine and arginine-rich domain and displays preference for monomethylated substrates. Specifically mediates the asymmetric dimethylation of histone H3 'Arg-2' to form H3R2me2a. H3R2me2a represents a specific tag for epigenetic transcriptional repression and is mutually exclusive with methylation on histone H3 'Lys-4' (H3K4me2 and H3K4me3). Also methylates histone H2A and H4 'Arg-3' (H2AR3me and H4R3me, respectively). Acts as a regulator of DNA base excision during DNA repair by mediating the methylation of DNA polymerase beta (POLB), leading to the stimulation of its polymerase activity by enhancing DNA binding and processivity. Methylates HMGA1. Regulates alternative splicing events. Acts as a transcriptional coactivator of a number of steroid hormone receptors including ESR1, ESR2, PGR and NR3C1. Promotes fasting-induced transcriptional activation of the gluconeogenic program through methylation of the CRTC2 transcription coactivator (By similarity). May play a role in innate immunity against HIV-1 in case of infection by methylating and impairing the function of various HIV-1 proteins such as Tat, Rev and Nucleocapsid protein p7 (NC). Methylates GPS2, protecting GPS2 from ubiquitination and degradation (By similarity). Methylates SIRT7, inhibiting SIRT7 histone deacetylase activity and promoting mitochondria biogenesis.
Synonyms: HRMT1L6; FLJ10559
Tractability: Small molecule: a structure with a bound ligand is known; a high-quality ligand is known. PROTAC: a small molecule that binds it is known.
Target class: Epigenetic regulator; Protein arginine methyltransferase; Writer; Protein methyltransferase
Chemical probes: EPZ020411, EPZ020411 (high quality), MS023 (high quality), MS049 (high quality), SGC6870 (high quality)
Gene: Protein-coding gene on chromosome 1 (107,056,674 to 107,067,636, forward strand). Ensembl gene ENSG00000198890.
Subcellular location: Nucleus
Subcellular location (Human Protein Atlas): Nucleoli; Nucleoplasm
Pathways (Reactome):
Chromatin organization: RMTs methylate histone arginines
Gene expression (Transcription): RUNX1 regulates genes involved in megakaryocyte differentiation and platelet function
Gene Ontology:
Molecular function: histone binding; histone H2AR3 methyltransferase activity; histone H3 methyltransferase activity; histone H3R2 methyltransferase activity; histone H4R3 methyltransferase activity; histone methyltransferase activity; protein binding; protein-arginine N-methyltransferase activity; protein-arginine omega-N asymmetric methyltransferase activity; protein-arginine omega-N monomethyltransferase activity; chromatin binding
Biological process: chromatin remodeling; negative regulation of DNA-templated transcription; positive regulation of cell cycle process; regulation of mitochondrion organization; base-excision repair; regulation of megakaryocyte differentiation; negative regulation of ubiquitin-dependent protein catabolic process; regulation of gene expression
Cellular component: nucleolus; nucleoplasm; nucleus
Genetic constraint (gnomAD): Loss-of-function variants: 23 observed, 30.96 expected, observed/expected ratio (o/e) 0.74, 90% interval 0.53 to 1.05. The upper end of that interval is the gene's LOEUF score, 1.05, which puts it in group 4 of 6, group 1 being the genes least tolerant of losing a copy. Missense variants: 528 observed, 545.89 expected, observed/expected ratio (o/e) 0.97, 90% interval 0.9 to 1.04. Synonymous variants: 265 observed, 244.45 expected, observed/expected ratio (o/e) 1.08, 90% interval 0.98 to 1.2.
Homologues: Orthologues: chimpanzee PRMT6 (100% identical), macaque PRMT6 (99% identical), guinea pig PRMT6 (95% identical), rat Prmt6 (94% identical), pig PRMT6 (93% identical), mouse Prmt6 (92% identical), dog PRMT6 (90% identical), tropical clawed frog prmt6 (53% identical), zebrafish prmt6 (50% identical), Drosophila melanogaster Art2 (28% identical). Paralogues in human: PRMT2 (35% identical), CARM1 (31% identical), PRMT3 (31% identical), PRMT8 (31% identical), PRMT1 (31% identical), PRMT9 (21% identical), PRMT7 (19% identical).
Diseases named in the same sentence as PRMT6 in open-access papers:
PRMT6 is named in the same sentence as 62 diseases in open-access papers, as found by Europe PMC text mining. Sharing a sentence is not in itself a finding about the gene and the disease. The quoted sentences say what the papers report.
breast carcinoma (21 papers, 2012 to 2025). "PRMT6 is also associated with estrogen-dependent breast cancer as it plays a role in estrogen signaling." (PMID 40869229, 2025). "Together, these data confirm that PRMT6 is an oncogene and represents a potential latent diagnostic marker for breast cancer." (PMID 36941223, 2023). "PRMT6 overexpression has been linked to the development of melanoma and breast cancer cell lines have undergone preclinical testing of PRMT6 inhibitors." (PMID 33440687, 2021). "PRMT6-mediated gene expression and alternative splicing changes are implicated in the pathophysiology of breast cancer." (PMID 34575100, 2021). "PRMT6 is associated with increased recurrence and promoted metastasis of breast cancer via the attenuation of p21." (PMID 33193750, 2020). "In addition, they demonstrated that abnormal expression of PRMT6 and PRMT6-dependent gene signature is associated with poorer clinical prognosis in patients with ER+ breast cancer." (PMID 35311114, 2022). "Results indicate that PRMT6 is upregulated in breast cancer, compared with normal tissues; higher levels of PRMT6 were correlated with poor overall survival in patients with breast cancer, confirming that PRMT6 expression is associated with breast cancer development, as previously reported." (PMID 36941223, 2023). "Here, it is shown that metformin impairs the growth of breast cancer cells by inhibiting PRMT6, a protein arginine methyltransferase primarily responsible for asymmetric dimethylation of histone H3 arginine 2 (H3R2me2a)." (PMID 41327885, 2025). "PRMT6 has been reported to simultaneously regulate transcriptional initiation and pre-mRNA splicing of a subset of target genes in human breast cancer cells." (PMID 39900436, 2025). "Silencing PRMT6 in breast cancer cells derepresses p21, inducing cell cycle arrest, senescence, and reduced tumor growth." (PMID 41204384, 2025). "In breast cancer, PRMT6 catalyzes asymmetric dimethylation of STAT3 at R729, which enhances its membrane localization, interaction with JAK2, and phosphorylation at Y705, thereby promoting metastatic potential." (PMID 41204384, 2025). "Recent literature indicates that PRMT6 promotes breast cancer migration and distant metastasis by methylating STAT3, thereby regulating the IL-6/STAT3 pathway." (PMID 38637831, 2024). "PRMT6‐knockdown MDA‐MB‐231 cells were established using lentivirus‐delivered short hairpin RNA (shRNA) for RNA‐seq analysis to examine how PRMT6 promotes breast cancer growth." (PMID 36941223, 2023). "In this study, we established that PRMT6 exerted a positive regulatory influence on breast cancer metastasis through both in vivo and in vitro experiments." (PMID 37813837, 2023). "Meanwhile, the PARP1 inhibitor Olaparib enhances clock gene expression, thus, reducing breast carcinogenesis, indicating that PARP1 inhibitors have potential antitumor effects in high‐PRMT6 expression breast cancer." (PMID 36941223, 2023). "Considering that epithelial‐mesenchymal transition (EMT) is the main pathway involved in invasion and metastasis leading to tumor progression, the levels of EMT markers were assessed to clarify the molecular role of PRMT6 in breast cancer metastasis." (PMID 36941223, 2023). "To elucidate the role of PRMT6 in breast cancer, we verified the mRNA expression levels of potential tumor suppressor genes (TSGs) and oncogenes." (PMID 36941223, 2023). "In sum, our study unveils the pivotal biological role of PRMT6-mediated STAT3 R729me2a in breast cancer metastasis and underscores the prospective utility of PRMT6 inhibitors as effective therapeutic strategies against STAT3-driven metastatic breast cancer." (PMID 37813837, 2023). "Further, PRMT6 enhanced breast cancer cell proliferation, invasiveness, metastasis, and EMT, thus, promoting cancer progression." (PMID 36941223, 2023). "Collectively, these phenotypic results suggest that PRMT6 represents a novel DNA repair factor required to sustain breast cancer progression." (PMID 36941223, 2023).
breast carcinoma (continued). "In overexpressing PRMT6 cells, Olaparib treatment reduced the proliferation and invasive ability of breast cancer cells compared with the control group, whereas PER3 deletion rescued these effects." (PMID 36941223, 2023). "The published datasets were analyzed to better understand the association between PRMT6, PARP1, DDB1, and PER3 in breast cancer." (PMID 36941223, 2023). "The current study sought to investigate the molecular mechanisms by which the PRMT6 complex promotes breast cancer progression." (PMID 36941223, 2023). "PRMT6 was observed overexpressed in breast cancer MCF7 cell lines, while the levels of thrombospondin-1 (TSP-1), an effective natural inhibitor of angiogenesis, were highly up-regulated in PRMT6-overexpressing cells." (PMID 35311114, 2022). "Experiments have also observed that PRMT6 mRNA expression level in the invasive ductal carcinoma (IDC) breast cancer is significantly lower than that in normal breast tissues." (PMID 35311114, 2022). "The protooncogene PELP1 interacts with PRMT6 and promotes the activation of estrogen receptor, cell proliferation and clonogenic capacity of the breast cancer cells." (PMID 34575100, 2021). "More than 30 human splicing factors have now been defined, and some of them are characterized as either proto-oncogenes, such as SRSF1, SRFS3, DAM1, and PELP1, or tumor suppressors, such as RBM and PRMT6, in breast cancer." (PMID 32110852, 2020). "PRMT6 has been reported to be overexpressed in bladder, lung and breast cancer cells, and the elevated levels observed in breast tumor samples by immunohistochemistry (IHC) were correlated with tumor stage." (PMID 27556302, 2016). "We conclude that PRMT6 acts as an oncogene in breast cancer cells, promoting growth and preventing senescence, making it an attractive target for cancer therapy." (PMID 22987071, 2012). "With the aim to mechanistically dissect the putative role of PRMT6 in the aetiology of breast cancer, we then switched to cancer cell lines." (PMID 22987071, 2012). "To study the role of PRMT6 in breast cancer, we raised a PRMT6 specific antibody and examined its expression levels in 37 tumour samples and matched control tissues." (PMID 22987071, 2012). "Furthermore, genetic disruption of the interaction between metformin and PRMT6 attenuates the inhibitory effect of metformin on breast cancer growth." (PMID 41327885, 2025). "Additionally, the data in GSE65194 showed that PRMT1, PRMT3, CARM1, PRMT5, and PRMT6 were highly expressed in basal-like breast cancer." (PMID 38476024, 2024). "Hence, the primary aim of the current study is to investigate the molecular mechanisms by which the PRMT6 complex promotes breast cancer progression." (PMID 36941223, 2023). "Moreover, PRMT6 overexpression led to a significant increase in the migration and invasive potential of breast cancer cells, while PRMT6 deletion eliminated metastatic capacity." (PMID 36941223, 2023). "Hence, although the PRMT6 and PARP1 inhibitors exhibit unique effects, targeting PARP1 and PRMT6 exerts synergetic effects on breast cancer progression by targeting the circadian rhythm." (PMID 36941223, 2023). "Therefore, PRMT6 plays an essential role on the development, metastasis, treatment, drug resistance and many other aspects of breast cancer." (PMID 35311114, 2022).
breast carcinoma (continued). "This suggests that PRMT6 methylation of Polβ is a mechanism that promotes genomic stability and thus may inhibit the development of breast cancer." (PMID 35311114, 2022). "Therefore, it can be concluded that PRMT6 is an essential component of estrogen signaling pathway in breast cancer cells." (PMID 35311114, 2022). "Based on the data presented, we can conclude that PRMT6 acts as an oncogene in breast cancer." (PMID 22987071, 2012). "We next sought to determine whether PRMT6 expression was required for growth and tumorigenicity of breast cancer cell lines." (PMID 22987071, 2012). "Therefore, to understand the molecular basis of the growth arrest induced by PRMT6 KD in breast cancer cells, we focused our attention on two key mediator of cellular senescence as follows: p16INK4A and CDKN1A/p21/Waf1/cip1 (p21)." (PMID 22987071, 2012). "Similarly to PRMT1, knockdown of PRMT6 inhibited estrogen-stimulated proliferation of breast cancer cells and impaired cell migration and invasion of U2OS cells." (PMID 23202904, 2012). "Here, we focus our investigation on PRMT6 and on its deregulation in breast cancer." (PMID 22987071, 2012). "Thus, PRMT6 expression was positively correlated with that of PARP1 in breast cancer samples." (PMID 36941223, 2023). "Hence, the PRMT6/PARP1/CRL4B complex might serve as an oncogenic target in breast cancers, and PRMT6 as a novel biomarker for PARP inhibitor monotherapy." (PMID 36941223, 2023). "Therefore, PRMT6 may be served as a therapeutic marker for breast cancer, but its exact effects on breast cancer need further study." (PMID 35311114, 2022). "To investigate the regulation of PRMT6 and PARP1 in breast cancer tissues, we assessed their protein levels in breast carcinoma samples of different histological grades, as well as in normal mammary tissues via IHC staining assays." (PMID 36941223, 2023). "The co‐staining results indicated that PRMT6 and PARP1 abundances were elevated in breast cancer samples and were positively correlated with histological grades." (PMID 36941223, 2023). "We also validated the co‐expression of PARP1, PRMT6, and PER3 in normal breast tissue and three different grades breast cancer tissues using immunofluorescent staining (IF)." (PMID 36941223, 2023). "In the context of breast cancer (BRCA), PRMT6’s engagement with the p21 promoter has been reported, resulting in the inhibition of p21 expression and the modulation of cellular senescence." (PMID 37813837, 2023). "We concluded that the PRMT6/PARP1/Cullin4B (CUL4B)‐Ring E3 ligase (CRL4B) complex transcriptionally represses PER3 and promotes breast cancer proliferation, invasion, and metastasis." (PMID 36941223, 2023). "The protein arginine methyltransferase 6 (PRMT6) serves as an oncogene in a myriad of solid tumors, including breast cancer." (PMID 36941223, 2023). "Analysis of online datasets further revealed augmented PRMT6, PARP1, CUL4B, and DDB1 levels in breast cancer tissues compared with normal tissues." (PMID 36941223, 2023). "In terms of therapeutic intervention, we demonstrated the significant capability of the PRMT6 inhibitor, EPZ020411, to curtail breast cancer metastasis both in vivo and in vitro." (PMID 37813837, 2023). "PRMT6 and PARP1 expression were elevated in breast cancer samples and were positively correlated with histological grade." (PMID 36941223, 2023). "The current study results indicate that PRMT6 binds to PARP1, recruiting the CRL4B complex which, together, stimulate histone methylation and ubiquitination modification, thereby promoting breast cancer progression." (PMID 36941223, 2023).